TNFRSF1A (TNF receptor superfamily member 1A)
Diseases named in the same sentence as TNFRSF1A in open-access papers (continued):
Sharing a sentence is not in itself a finding about the gene and the disease.
Stroke (38 papers, 2012 to 2025). Sudden impairment of blood flow to a part of the brain due to occlusion or rupture of an artery to the brain. "Stroke-associated microglial clusters showed microglia-specific dysregulation of PANoptosis regulators (MCL1, TNFRSF1A, and STAT3), with TNFRSF1A upregulated in the ischemic core." (PMID 41235394, 2025). "TNFRSF1A has also been shown to mediate the protective role of cerebellar fastigial nucleus stimulation in reducing the severity of post-stroke depression." (PMID 35432334, 2022). "The non-canonical pathway integrates signals from a subset of TNF receptor family members including Tnfrsf1a and Tnfrsf1b, both known to be involved in the inflammatory responses to stroke." (PMID 23251410, 2012). "Four hub PANRGs (MCL1, TNFRSF1A, STAT3, Hsp90aa1) were identified, enriched in MAPK and PI3K-AKT signaling pathways and negatively associated with oxidative phosphorylation, suggesting their involvement in stroke pathogenesis." (PMID 41235394, 2025). "Collectively, these findings suggest that TNFRSF1A may serve as a promising therapeutic target in stroke." (PMID 41235394, 2025). "The relatively small sample size may limit the generalizability of our findings, and the precise mechanisms by which TNFRSF1A contributes to stroke pathophysiology are still unclear." (PMID 41235394, 2025). "Female MMP-3 KO stroke brains showed downregulation of the macrophage classical activation signaling genes Tnf and Tnfsf9, and decreased expression of the acute phage response genes Tnfrsf1a, Jun, Tnfrsf1b, Il6, Tnf, and Fos." (PMID 39000490, 2024). "Furthermore, female MMP-3 KO stroke brains showed decreased expression of apoptosis signaling genes Casp6, Tnfrsf1b, Tnfrsf1a, and Tnf, and downregulated expression of matrix metalloprotease genes Mmp14, Mmp9, and Mmp11." (PMID 39000490, 2024). "Our results indicate that Tnfrsf1a and Tnfrsf1b mRNAs are robustly upregulated in the early stage of ischemic damage in both age groups, but its expression was robustly increased by day 14 post-stroke in the aged brains only." (PMID 24672479, 2014). "Validation in GSE35338 and GSE137482 showed consistent upregulation of MCL1, TNFRSF1A, and STAT3 in stroke, supporting their role as candidate biomarkers." (PMID 41235394, 2025). "Collectively, these findings suggest that MCL1, TNFRSF1A, and STAT3 regulate PANoptosis and contribute to stroke progression." (PMID 41235394, 2025). "Tnfrsf1a, Tnfrsf1b, and Nfkb2 are known to be involved in inflammatory responses to stroke via noncanonical I-kappa B kinase/NF-kappa B cascade." (PMID 29516010, 2018).
Sepsis (36 papers, 2005 to 2025). Sepsis is defined as life-threatening organ dysfunction caused by a dysregulated host response to infection. "In conclusion, our study showed that TNFRSF1A is closely associated with sepsis-induced liver injury, which provides a potential diagnostic signature for septic liver injury and a basis for exploring the roles the liver plays in defense homeostasis during sepsis." (PMID 36299685, 2022). "Further research was conducted to reveal the associations between m6A patterns and inflammatory factors, including interleukin (IL)-1β, IL-8, IL-10, IL-11 and TNF receptor superfamily member 1A (TNFRSF1A), in sepsis." (PMID 36781867, 2023). "In our experimental study, TNFRSF1A expression was detected in the liver, lung, and kidney tissues of sepsis mice, and only TNFRSF1A in the liver was significantly downregulated, which was consistent with the bioinformatics analysis." (PMID 36299685, 2022). "Although the mortality of TNFRSF1A−/− mice in sepsis was comparable with wildtype mice, it is still undeniable the important role of TNFRSF1A in septic liver injury." (PMID 36299685, 2022). "In sepsis, TNFRSF1A is a key participant during Staphylococcus aureus infections and is associated with the bacterial clearance from the spleen." (PMID 36299685, 2022). "The significant increase of soluble TNFRSF1A in the circulation is closely related to sepsis." (PMID 36299685, 2022). "Therefore, our results cannot exclude variant associations with weaker effects between severe sepsis and the other three candidate genes (LTA, TNFRSF1A, TNFRSF1B)." (PMID 23029405, 2012). "However, to date, only one study investigated the role of TNFRSF1A and TNFRSF1B polymorphisms in sepsis susceptibility and mortality." (PMID 23029405, 2012). "However, up to now, only one case control study investigated associations between TNFRSF1A and TNFRSF1B polymorphisms and sepsis susceptibility." (PMID 23029405, 2012). "The objective of this study was to investigate whether genetic variation in TNF, LTA, TNFRSF1A and TNFRSF1B was associated with susceptibility to or death from severe sepsis in Chinese Han population." (PMID 23029405, 2012). "Therefore, the decreased TNFRSF1A protein expression in the liver tissue of the sepsis model combined with the downregulation of gene expression verified that TNFRSF1A may serve as a specific biomarker of septic liver damage and liver immunoregulation." (PMID 36299685, 2022). "TNFRSF1A may serve as an intervention target to alleviate and treat sepsis in the future." (PMID 36299685, 2022). "Ten SNPs in TNF, LTA, TNFRSF1A and TNFRSF1B were genotyped in samples of patients with severe sepsis (n = 432), sepsis (n = 384) and healthy controls (n = 624)." (PMID 23029405, 2012). "Using soluble TNFRSF1A to neutralize TNF reduces organ damage and mortality in sepsis rat." (PMID 36299685, 2022). "Association analysis of SNPs in TNF, LTA, TNFRSF1A and TNFRSF1B between survivors and non-survivors of severe sepsis patients." (PMID 23029405, 2012). "Considering the important role of TNF-α, LT-α, TNFR1 and TNFR2 in the pathogenesis of severe sepsis, we hypothesized that genetic variation in TNF, LTA, TNFRSF1A and TNFRSF1B might be associated with susceptibility to and outcomes from severe sepsis in Chinese Han population." (PMID 23029405, 2012).
type 2 diabetes (31 papers, 2013 to 2026). "DAVID was used to identify the functions of these genes, and TIRAP, TNFRSF1A, CASP1, CSF1, and ITGAM were associated with type 2 diabetes." (PMID 39194753, 2024). "Among the effector genes predicted by the Type 2 Diabetes Knowledge Portal, TNFRSF1A expression levels are positively correlated with HbA1c levels." (PMID 39916961, 2024). "TIRAP, TNFRSF1A, CASP1, CSF1, and ITGAM are associated with the development of type 2 diabetes, a condition linked to obesity." (PMID 39194753, 2024). "Among subjects at higher risk of type 2 diabetes, an acute postprandial intervention of MUFA breakfast (72 E%) containing macadamia nut oil showed that several inflammatory genes were upregulated in subcutaneous adipose tissue (MCP-1, IL-1β, IL-6, IL-6R, TNF-α and TNFRSF1A)." (PMID 28076613, 2017).
psoriasis (28 papers, 2014 to 2025). An autoimmune condition characterized by red, well-delineated plaques with silvery scales that are usually on the extensor surfaces and scalp. "In addition, polymorphisms in TNFRSF1A are associated with psoriasis, UC, and CD." (PMID 39297883, 2024). "In psoriasis, TNF-α binds to tumor necrosis factor receptor 1 (TNFR1/TNFRSF1A) and receptor 2 (TNFR2), activating downstream NF-κB and MAPK signaling pathways." (PMID 40948748, 2025).
Obesity (27 papers, 2012 to 2026). Accumulation of substantial excess body fat. "For instance, TNFRSF1A, linked to obesity, significantly impacted the proliferation and migration of kidney cancer cells." (PMID 40928391, 2026). "Since TNFα has been implicated as a link between obesity and insulin resistance this circular loop [(TWEAK)-(miR-715)-(TNFrsf1a)] provides some experimental evidence for this particular miRNA's connection with caloric pathway." (PMID 22245972, 2012). "First, we identified gene sets related to the function of each obesity-related serum factor: HG/HI (Insr, Irs1, Rps6kb1, Slc2a4, Slc2a5, Slc2a1), TNF-α (Tnfrsf1a, Tradd, Traf2, Fadd), IL-6 (Il6ra, Il6st, Jak1), and fatty acids (PA, LA, Chol; Ffar1, Ffar4, Ppara, Pdk4, Pgc1a)." (PMID 37047207, 2023).
atherosclerosis (26 papers, 2009 to 2025). A disease characterized by the build-up of fatty material and calcium deposition in the arterial wall resulting in partial or complete occlusion of the arterial lumen. "Others have also found an association between the R92Q polymorphism of TNFRSF1A and the development of atherosclerosis as well as inconsistency between the presence of the R92Q in patients with AMI and IS and disease occurrence." (PMID 35432334, 2022). "However, Tnfrsf1a−/− mice on a proatherogenic Apoe−/− background showed reduced atherosclerosis, and the data pointed to the key role of TNFR1 expressed in arteries." (PMID 33053859, 2020). "Furthermore, TNFRSF1A demonstrated substantial enrichment in the NF-kappa B signaling pathway, MAPK signaling pathway, Fluid shear stress and atherosclerosis, and Insulin resistance." (PMID 40918148, 2025).
glioma (24 papers, 2007 to 2025). A benign or malignant brain and spinal cord tumor that arises from glial cells (astrocytes, oligodendrocytes, ependymal cells). "Besides, TNFRSF1A was verified to be associated to the molecular classification of gliomas, and it was highly upregulated in Mes subtype and downregualted in PN subtype of gliomas in this study." (PMID 32257943, 2020). "Our findings provide a further understanding of the progression of gliomas, and Mesenchymal-associated TNFRSF1A might be a promising target of diagnosis, therapy, and prognosis of gliomas." (PMID 32257943, 2020). "Notably, TNFRSF1A was preferentially upregulated in the Mesenchymal subtype gliomas (Mesenchymal-associated)." (PMID 32257943, 2020). "Therefore, TNFRSF1A was a novel Mesenchymal-associated biomarker in molecular classification of gliomas." (PMID 32257943, 2020). "Likewise, TNFRSF1A expression of gliomas carrying 1p/19q codeletion or IDH mutation was lower than the corresponding glioma samples." (PMID 32257943, 2020). "Thus, TNFRSF1A expression was associated with poor prognosis in gliomas." (PMID 32257943, 2020). "Similarly in the another dataset CGGA mRNAseq_325, univariate analysis revealed that a total of 9 factors were associated with OS of gliomas, including TNFRSF1A expression, age, WHO grade, PRS_type, histology, Radio_status, Chemo_status, IDH_mutation_status and 1p19q_codeletion_status." (PMID 32257943, 2020). "TCGA database analysis further revealed a strong positive correlation between NFE2L2 (the gene encoding NRF2) and CD44, TNFRSF1A, and ANXA1 expression in glioma tissues." (PMID 40583858, 2025). "Moreover, TNFRSF1A purportedly may serve as a diagnostic and prognostic biomarker in gliomas." (PMID 35453806, 2022). "The Kaplan-Meier plots were performed to examine the relationship between the TNFRSF1A expression and OS of glioma patients." (PMID 32257943, 2020). "The results of colony formation assay further demonstrated that colony numbers of glioma cells were significantly inhibited while TNFRSF1A was silencing." (PMID 32257943, 2020). "Based on the CCK-8 assay, proliferative capacity of glioma cells transfected with TNFRSF1A siRNA2was significantly compared to those treated with si-NC." (PMID 32257943, 2020). "The boxplots precisely revealed that TNFRSF1A expression was upregulated in gliomas (LGGs and GBMs) compared with the normal corresponding samples using the GEPIA2." (PMID 32257943, 2020). "Taken together, downregulation of TNFRSF1A inhibited glioma cell proliferation and migration in vitro." (PMID 32257943, 2020). "In this study, TNFRSF1A was identified as a biomarker of molecular subtypes and an independent prognostic factor of gliomas based on the integrated bioinformatics analyses." (PMID 32257943, 2020). "Collectively, TNFRSF1A expression was upregulated in gliomas than normal samples, and related to glioma histology and WHO grade." (PMID 32257943, 2020). "In this study, an integrated bioinformatics analysis of the public databases found that the brown co-expression module and the biomarker TNFRSF1A was identified to be strongly related to WHO grade of gliomas." (PMID 32257943, 2020). "After transfection of glioma cells with si-NC or TNFRSF1A siRNAs, knockdown efficiency of TNFRSF1A siRNA2 was most obvious in both U251 and U87." (PMID 32257943, 2020). "TNFRSF1A is highly expressed in glioma tissues compared with normal brain tissues, and is related to poor prognosis of glioma patients." (PMID 32257943, 2020). "Cox regression analysis of TNFRSF1A expression as a survival indicator of gliomas in CGGA mRNAseq_325." (PMID 32257943, 2020). "Overall, TNFRSF1A was identified by an integrated informatics analyses such as WGCNA, and transcriptome analyses further revealed that TNFRSF1A expression was upregulated in glioma samples compared with the normal brain samples." (PMID 32257943, 2020).
glioma (continued). "Knockdown of TNFRSF1A suppressed glioma cells proliferation, migration and invasion in vitro, which further confirmed the important values of TNFRSF1A on glioma progression." (PMID 32257943, 2020). "Cox regression analysis of TNFRSF1A expression as a survival indicator of gliomas in CGGA mRNA-array_301." (PMID 32257943, 2020). "The clinical correlation analyses also showed that TNFRSF1A expression was significantly associated with histology and WHO grade of gliomas." (PMID 32257943, 2020). "Knockdown of TNFRSF1A inhibited the proliferation and migration of glioma cell lines in vitro." (PMID 35481240, 2022). "Others were robust and shared across most samples such as CD74 receptor binding to MIF, COPA, or APP as cognate ligands and SPP1-CD44 (myeloid to glioma signaling) and TNFRSF1A-GRN, PGRMC2-CCL4L2, MDK-SORL1 or LRP1, and GPR37L1-PSAP (glioma to myeloid signaling)." (PMID 35140215, 2022). "Using the same antibody HPA004102 from the IHC-based HPA database, protein expression level of GNG5 protein increased in the order of normal brain tissue, LGG and HGG among different patients, which further confirmed the important role of TNFRSF1A in gliomas at the protein level." (PMID 32257943, 2020). "Recurrent gliomas have higher expression level of TNFRSF1A than primary gliomas." (PMID 32257943, 2020). "Based on the datasets from GEO, TCGA and CGGA, TNFRSF1A could differentiate the various subtypes of gliomas, and more importantly, its expression level in Mesenchymal subtype gliomas was higher than other subtypes." (PMID 32257943, 2020). "Furthermore, ROC analysis found that TNFRSF1A was capable of predicting the pathological diagnosis of gliomas in GSE4290, GSE68848 and TCGA, respectively (AUC>0.7)." (PMID 32257943, 2020). "Knockdown of TNFRSF1A inhibited glioma cell proliferation and migration." (PMID 32257943, 2020). "Knockdown of TNFRSF1A suppressed the progression of glioma cell lines in vitro." (PMID 32257943, 2020). "More importantly, the expression level of TNFRSF1A was positively associated with WHO grade in the eight datasets, including GSE4290, GSE68848, CGGA (mRNA-array_301, mRNAseq_325 and mRNAseq_693), TCGA_glioma, GSE4271 and GSE4412, respectively." (PMID 32257943, 2020). "Furthermore, glioma or LGG patients with high TNFRSF1A expression had a shorter disease-free survival (DFS) than the low expression group using GEPIA2." (PMID 32257943, 2020). "Transwell assay showed that TNFRSF1A knockdown significantly reduced the migration of glioma cells." (PMID 32257943, 2020). "Glioma samples with older age (≥60) or microvascular proliferation or necrosis or Chemo_status (chemotherapy status) or treatment and therapy status have higher TNFRSF1A expression compared with the corresponding samples." (PMID 32257943, 2020). "KEGG enrichment analysis showed that TNFRSF1A could regulate the tumorignenesis of gliomas via activating the MAPK signaling pathway." (PMID 32257943, 2020). "Knockdown of TNFRSF1A inhibited proliferation and migration of glioma cell lines in vitro." (PMID 32257943, 2020). "Thus, TNFRSF1A might be a novel biomarker of diagnosis, therapy, and prognosis related to progression of gliomas." (PMID 32257943, 2020). "Moreover, the expression level of TNFRSF1A was associated with WHO grade and other clinical features such as molecular subtypes, and was found to serve as an independent prognostic indicator of OS in gliomas." (PMID 32257943, 2020). "Studies have shown that the immune checkpoint ligands ICOS, BTLA, TNFRSF1A, and TNFRSF1B all contribute to glioma immune evasion." (PMID 36882457, 2023). "Recently, ABCC3 has been included in gene signatures (ABCC3, CD44, TNFRSF1A, and MGMT24; ABCC3, SMC4, EMP3, WEE1, and HIST1H2BK44) that classify glioma patients in agreement with therapeutic response to chemotherapeutic agents, including TMZ." (PMID 36585418, 2022).
glioma (continued). "Overexpressed TNFRSF1A was strongly related to clinical features such as WHO grade, and functioned as an independent poor prognostic predictor of glioma patients." (PMID 32257943, 2020). "However, the role of TNFRSF1A in the development of gliomas still remains unclear." (PMID 32257943, 2020). "Taken together, these results from the two datasets revealed that TNFRSF1A expression and WHO grade as well as 1p19q_codeletion_status were independent prognostic indicators of OS in gliomas." (PMID 32257943, 2020). "The brown module was found to be strongly related to WHO grade of gliomas, and KEGG pathway analysis demonstrated that TNFRSF1A was enriched in MAPK signaling pathway and TNF signaling pathway." (PMID 32257943, 2020). "And glioma patients with molecular characteristics such as IDH mutation or 1p/19q codeletion had a lower expression level of TNFRSF1A than the glioma samples without these characteristics." (PMID 32257943, 2020). "We found that IngC promoted modulation in proteins related to stress and cell cycle, as well as anti-apoptotic and pro-apoptotic protein expression, with special reduction in the levels of pro-apoptotic BAX, BAD, TNRI/TNFRSF1A, and FASTNFR6/CD95, were observed for most of glioma cell lines overtime." (PMID 31771098, 2019). "Prior to the analysis, glioma samples without survival information were cut off and obtained samples were classified into two groups: low expression group and high expression group, according to the median of TNFRSF1A expression." (PMID 32257943, 2020). "Moreover, glioma samples with some features (including older ages, high WHO grades, microvascular proliferation and necrosis) had a higher expression level of TNFRSF1A than the corresponding samples, suggesting that TNFRSF1A might be associated with poor prognosis." (PMID 32257943, 2020).